NLRP3 (NLR family pyrin domain containing 3)
Diseases named in the same sentence as NLRP3 in open-access papers (continued):
Sharing a sentence is not in itself a finding about the gene and the disease.
non-alcoholic steatohepatitis (continued). "Also, SLC7A11 impaired NLRP3 inflammasome expression in nonalcoholic steatohepatitis advocating the involvement of ferroptosis in NLRP3 activation." (PMID 40622464, 2025). "In addition, LRG improves nonalcoholic steatohepatitis by inhibiting the activation of NLRP3 inflammatory bodies and cell charring." (PMID 38364258, 2024). "In addition, MCs can also induce NLRP3-mediated inflammatory responses in liver cells, which will increase the expression of IL-1β in cells and promote the progression of non-alcoholic steatohepatitis." (PMID 37104231, 2023). "Adiponectin could inhibit NLRP3 inflammasome activation in nonalcoholic steatohepatitis or cerebral ischemia-reperfusion injury." (PMID 35784553, 2022). "One study has shown that arsenic trioxide (As2O3) could induce nonalcoholic steatohepatitis, increase autophagy, NLRP3 inflammasome activation, and lipid accumulation, which leads to lipid-related gene dysregulation." (PMID 32313131, 2020). "Additionally, inhibition of the SHP-2/PI3K/NLRP3 axis has been reported to reduce pyroptosis and ameliorate non-alcoholic steatohepatitis, while SHP-2 has also been implicated in promoting pyroptosis and activating the NLRP3 inflammasome in renal cell carcinoma." (PMID 41322436, 2025). "The NLRP3 inflammasome plays a critical role in host immune responses; However, its aberrant activation promotes the development of multiple chronic liver diseases (including viral hepatitis, alcoholic and nonalcoholic steatohepatitis, and liver cancer, among others) and ALI." (PMID 36834481, 2023). "Thus, inhibition of NLRP3 inflammasome activation in KCs may be an effective way to limit the shifting of NAFLD to non-alcoholic steatohepatitis (NASH)." (PMID 28427239, 2017). "NLRP3 inflammasome activation is required for liver inflammation and fibrosis in mouse models of NAFLD and non-alcoholic steatohepatitis (NASH)." (PMID 40667485, 2025). "In a mouse model of nonalcoholic steatohepatitis (NASH), Kupffer cells (resident macrophages) exhibited increased mtROS production, decreased ∆Ψmt, increased mtDNA release into the cytosol and NLRP3 inflammasome activation." (PMID 40264103, 2025). "NLRP3 is highly activated and expressed during the progression from NAFLD to non-alcoholic steatohepatitis." (PMID 38566171, 2024). "It has been postulated that inflammasomes, in particular the NLRP3 (NLR family pyrin domain containing 3) inflammasome, mediate the necroinflammation and fibrosis that characterize nonalcoholic steatohepatitis (NASH) by engaging innate immune responses." (PMID 36641116, 2023). "Abnormal activation of innate immunity is also reported in non-alcoholic steatohepatitis (NASH) and non-alcoholic fatty liver disease (NAFLD), which require NOD-like receptor protein 3 (NLRP3) inflammasome activation for fibrosis development." (PMID 29374495, 2018). "Similarly, in non-alcoholic steatohepatitis (NASH), Kupffer cell activation via TLR4 and NLRP3 inflammasomes promotes release of cytokines such as IL-1β and IL-18." (PMID 41585231, 2025). "Among them, S1PR1 controls the expression of IL-1β in response to Newcastle disease virus by modulating the NLRP3/caspase-1 inflammasome pathway and enhances inflammation and fibrosis in the kidney, while S1PR4 promotes nonalcoholic steatohepatitis by activating NLRP3 inflammasomes." (PMID 38003456, 2023). "Hepatic mRNA levels for NLRP3, ASC, and caspase-1 are up-regulated in experimental models of non-alcoholic fatty liver disease, but full activation of inflammasome has only been evidenced in non-alcoholic steatohepatitis." (PMID 31547621, 2019). "In a murine model of non-alcoholic steatohepatitis, fibrosis was not reversed by IL-1Ra treatment, indicating that other regulators of NLRP3 inflammasome are involved in fibrogenesis promotion." (PMID 32038610, 2019).
non-alcoholic steatohepatitis (continued). "Here, we focus on recent advances on the potential role of NLRP3 inflammasome activation in the progression of CLD, including viral hepatitis, non-alcoholic steatohepatitis and alcoholic liver disease, and in particular, its ability to alleviate liver inflammation in animal models." (PMID 29312290, 2017). "NLRP3 activation is also involved in initiating and promoting the development of nonalcoholic steatohepatitis (NASH); in vivo and in vitro experimental studies demonstrated that activation of the NLRP3 inflammasome is mainly associated with NASH, but not with steatosis." (PMID 38068879, 2023). "Background and Aims: Activation of the inflammasome NLRP3 (NOD-, LRR- and pyrin domain containing 3) contributes to the development of non-alcoholic fatty liver disease (NAFLD) and progression to non-alcoholic steatohepatitis (NASH)." (PMID 34513923, 2021). "It has been postulated that the NLRP3 inflammasome is also a key sensor of PAMPs/DAMPs in nonalcoholic fatty liver disease (NAFLD) and a trigger for necroinflammation and fibrosis, resulting in progression to fibrosing nonalcoholic steatohepatitis (NASH)." (PMID 36641116, 2023).
non-alcoholic fatty liver disease (86 papers, 2012 to 2026). "In a previous study, it was reported that thioredoxin-interacting protein (TXNIP), an activator of NOD, LRR, and PYD domains-containing protein 3 (NLRP3) inflammasome, is associated with nonalcoholic fatty liver disease and T1DM." (PMID 32719778, 2020). "The activation of NOD-like receptor family pyrin domain containing 3 (NLRP3) inflammasome is closely associated with the development and progression of non-alcoholic fatty liver disease (NAFLD) induced by a high-fat diet." (PMID 27075683, 2016). "Another study showed that bisphenol A (BPA) enhances OGT-mediated O-GlcNAcylation of NLRP3, leads to abnormal lipid accumulation, and induces pyroptosis in HepG2 cells, thus accelerating the progression of non-alcoholic fatty liver disease (NAFLD) in vitro." (PMID 41059334, 2025). "Overall, the SMS extract suppresses pyroptosis in non-alcoholic fatty liver disease through the TXNIP/NLRP3 pathway." (PMID 40926986, 2025). "An expanding body of evidence highlights the central role of NLRP3 inflammasomes in the development of numerous liver conditions, encompassing alcoholic and nonalcoholic fatty liver diseases, as well as liver injury." (PMID 39949920, 2025). "Exogenous H2S has also been observed to improve outcomes in non-alcoholic fatty liver disease by inhibiting the ER stress/NLRP3 inflammasome pathway." (PMID 40136669, 2025). "In parallel, another study explored the impact of OGT-mediated O-GlcNAcylation induced by bisphenol A on NLRP3 stability and cell pyroptosis in non-alcoholic fatty liver disease (NAFLD)." (PMID 39742284, 2024). "As previously shown, mangiferin modulated the AMPK and NLRP3 signal pathways to alleviate nonalcoholic fatty liver disease (NAFLD)." (PMID 39376609, 2024). "ADAR1 alleviates high-fat diet-induced nonalcoholic fatty liver disease by inhibiting NLRP3 inflammasomes." (PMID 39403253, 2024). "For instance, TIL has been reported to attenuate hepatic inflammation in non-alcoholic fatty liver disease (NAFLD) by inhibiting NLRP3 inflammasome activation." (PMID 39388398, 2024). "Knockout mouse models suggested that inhibition of the NLRP3 inflammasome reduced liver inflammation, indicating that the NLRP3 inflammasome is involved in the progression of non-alcoholic fatty liver disease (NAFLD)." (PMID 37762434, 2023). "Lebeaupin and colleagues demonstrated that the ER stress signaling pathway increased NLRP3 inflammasome activation and hepatocyte death and consequently led to nonalcoholic fatty liver disease." (PMID 33613822, 2021). "There is evidence that failure to activate the NLRP3 inflammasome can lead to gut–liver axis derangement, gut dysbiosis, and a worsened phenotype in a mouse model of non-alcoholic fatty liver disease (NAFLD)." (PMID 31632284, 2019). "Activation of thioredoxin-interacting protein (TXNIP)/nod-like receptor protein 3 (NLRP3) inflammasome plays a critical role in pathogenesis of non-alcoholic fatty liver disease." (PMID 30429827, 2018). "Using NLRP3 KO mice, it was also reported that NLRP3 inflammasome activation is required for fibrosis development in non-alcoholic fatty liver disease (NAFLD)." (PMID 27247426, 2016). "Furthermore, studies in animals have demonstrated that naringenin mitigates non-alcoholic fatty liver disease by down-regulating the NLRP3/NF-κB pathway in mice." (PMID 39273450, 2024). "In addition, it has been reported that the NLRP3 inflammasome is inhibited by ECE in non-alcoholic fatty liver disease and muscle atrophy." (PMID 38138587, 2023). "Moreover, patients with severe nonalcoholic fatty liver disease showed increased levels of NLRP3 and IL-1β mRNA that correlated with the expression of COL1A1, a marker of liver fibrosis." (PMID 36669831, 2023).
non-alcoholic fatty liver disease (continued). "For instance, excessive activation of STING in liver is associated with the progression of nonalcoholic fatty liver disease by strengthening macrophage‐mediated liver inflammation and fibrosis; STING pathway regulates the activation of NLRP3 inflammasome in bone marrow cells and cardiomyocytes." (PMID 35957622, 2022). "Additionally, verapamil can treat non‐alcoholic fatty liver disease by inhibiting the TXNIP/NLRP3 pathway and reducing the level of IL‐1β and IL‐18 to attenuate hepatic metaflammation." (PMID 34031983, 2021). "In animal models of nonalcoholic fatty liver disease, we found that GLP-1 receptor agonists protected the livers of mice with nonalcoholic fatty liver disease by enhancing the liver autophagy/mitophagy pathway, reducing oxidative stress damage, and inhibiting NLRP3 inflammasomes." (PMID 34912814, 2021). "This study is aimed at investigating whether exenatide (Exe) delays the progression of nonalcoholic fatty liver disease (NAFLD) in C57BL/6 mice by targeting the NLRP3 inflammasome through the autophagy/mitophagy pathway." (PMID 29849583, 2018). "Likewise, pharmacological inhibition of NLRP3 inflammasome can also prevent HFD-induced non-alcoholic fatty liver disease with improved insulin sensitivity, and reduced liver damage accompanied by decreased caspase-1 activity and IL-1β expression levels versus wild-type mice." (PMID 37336361, 2023). "Search terms included combinations of "non-alcoholic fatty liver disease", "NAFLD", "NASH", "NLRP3 inflammasome", "traditional Chinese medicine", "TCM", "herbal medicine", "syndrome differentiation", and "precision medicine"." (PMID 42310899, 2026). "Apigenin has demonstrated potential in alleviating non-alcoholic fatty liver disease (NAFLD) and atherosclerosis by inhibiting NLRP3 inflammasome activation in mice with high-fat diets." (PMID 39966334, 2025). "For instance, in nonalcoholic fatty liver disease (NAFLD), GAS5 acts as a competing endogenous RNA (ceRNA) for miR-28a-5p, which has been demonstrated to promote pyroptosis through MARCH7-mediated NLRP3 activation, thereby exerting a protective effect." (PMID 39941145, 2025). "In line with this, 8-week endurance exercise reduces the cytosolic ox-mtDNA levels in hepatocytes of mice with nonalcoholic fatty liver disease (NAFLD), thereby inhibiting the overactivation of the NLRP3 inflammasome." (PMID 40243714, 2025). "Beyond immune cell-mediated liver injury, hepatocytes in patients with non-alcoholic fatty liver disease (NAFLD) and alcoholic steatohepatitis can directly activate the NLRP3-caspase-1 or DAG-PKCδ-NLRC4 inflammasomes, inducing pyroptosis." (PMID 39994107, 2025). "In a mouse model of NAFLD (Nonalcoholic fatty liver disease), GW501516, a specific PPARβ/δ ligand, inhibited the activation of NLRP3, NLRP6, and NLRP10 and decreased the production of pro-inflammatory molecules induced by high fat diet and LPS." (PMID 34829605, 2021). "Another two inflammasomes, NLRP3 and NLRP6, have also been reported to negatively regulate the progression of non-alcoholic fatty liver disease (NAFLD)." (PMID 30319645, 2018). "Previous work has studied the role of Nlrp3 and another member of the NLR inflammasome family, Nlrp6, in the context of nonalcoholic fatty liver disease (NAFLD)." (PMID 24453428, 2013). "Among the inflammasomes, studies have highlighted the importance of the NLRP3 inflammasome in many inflammatory disorders, such as ALD, obesity, type 2 diabetes, non-alcoholic fatty liver disease (NAFLD), and metabolic syndrome." (PMID 34630100, 2021). "In animal models, ezetimibe reduced inflammatory response and promoted autophagy, which resulted in neuroprotection or improvement of nonalcoholic fatty liver disease (NAFLD) via AMP protein kinase (AMPK) activation and inhibition of NLR family pyrin domain containing 3 (NLRP3) inflammasome." (PMID 32183405, 2020).
non-alcoholic fatty liver disease (continued). "However, a report on nonalcoholic fatty liver disease showed that MCC950 can reduce inflammation and NF-κB activation by inhibiting NLRP3." (PMID 32595419, 2020). "FOXO3 restores autophagy flux and attenuates the activation of the NLRP3 inflammasome in Kupffer cells by promoting the transcription of Bim (BCL2L11), suggesting that this could be a potential therapeutic target in non-alcoholic fatty liver disease and other obesity-related diseases." (PMID 36881352, 2023). "Nonalcoholic fatty liver disease (NAFLD), which promotes serious health problems, is related to the increase in the nucleotide-binding oligomerization domain-like receptor family, pyrin domain containing 3 (NLRP3) inflammasome and pyroptosis by a high-fat diet (HFD)." (PMID 34070893, 2021).
kidney damage (76 papers, 2011 to 2026). "We further applied scRNA‐seq to elucidate the therapeutic mechanism of BL23 acupuncture in HUA‐induced nephropathy and explored the potential association of this alteration with NLRP3 inflammasome and JAK2/STAT3 signaling pathways." (PMID 41278550, 2025). "The NOD-like receptor signaling pathway, especially the NLRP3 inflammasome, is associated with the occurrence and development of the disease and is related to the degree of kidney damage in SLE patients." (PMID 40297850, 2025). "Together with other nephropathy indicators such as proteinuria, blood pressure, blood C3 levels and renal pathology, we will further investigate the potential of C3aR and the NLRP3 inflammasome as diagnostic and prognostic markers of CKD." (PMID 38082306, 2023). "Priming and activation of the NLRP3 inflammasome have been linked to several clinical markers of nephropathy including proteinuria and albuminuria, in addition to morphological changes including mesangial expansion." (PMID 35755447, 2022). "As a pathogen-associated molecular pattern, uric acid can cause the activation of NLRP3 inflammasome and subsequent release of IL-1β and IL-18 and lead to severe kidney damage." (PMID 35309342, 2022). "Chronic inflammation is a hallmark of retinopathy and nephropathy, with induction of morphological and phenotypic cell changes linked to upstream activation of the NLRP3 inflammasome." (PMID 35054783, 2022). "Consistently, our previous study also found the activation of NLRP3 signaling in TCE-induced kidney damage in mice, which was associated with renal C5b-9 deposition." (PMID 35656289, 2022). "The activated NLRP3 inflammasome stimulates the secretion of IL-1β and IL-18 and causes severe kidney damage." (PMID 35382689, 2022). "Crystalline nephropathy (heterogeneous nephropathy characterized by severe symptomatology from crystal embolization to kidney stones in the urethra) is also associated with canonical NLRP3 inflammasome." (PMID 32410864, 2020). "Blockade of IL-1β and NLRP3 inflammasome activation by IL-1Ra significantly attenuated renal tubular injury and function loss in AA-induced nephropathy." (PMID 31616439, 2019). "Hence, our research suggested that the activation of the NLRP3 inflammasome is implicated in the onset and advancement of nephropathy induced by STZ." (PMID 40458807, 2025). "Therefore, targeting the NLRP3 inflammasome is of obvious therapeutic potential in the future management of both nephropathy and other age-associated morbidities." (PMID 35755447, 2022). "The relationship between high NLRP3 levels and tissue damage in LN was already recognized in previous studies suggesting that an inhibition of NLRP3 inflammasome activity can diminish the acute inflammation and kidney damage associated in mice and human models." (PMID 34830358, 2021). "Our characterization of the mitochondrial/NLRP3 inflammasome axis may provide new insight into the pathogenic progression of Aldo-induced kidney damage." (PMID 27014913, 2016). "Experimental induction of DN in rats through a high-fat diet/streptozotocin regimen showed elevated expression of IL-1β, NLRP3, and caspase 1, accompanied by severe kidney damage." (PMID 40458807, 2025). "Many studies have described activation of the NLRP3 inflammasome pathway in response to kidney damage." (PMID 40362638, 2025). "Above all, scRNA‐seq analysis demonstrated that EA exerts anti‐inflammatory effects and reduces the IL‐1β expression in treating HUA‐induced nephropathy through downregulation of both the NLRP3 inflammasome and the JAK2/STAT3 signaling pathway." (PMID 41278550, 2025). "Fecal microbiota transplantation (FMT) experiments also revealed that HUA microbiota can exacerbate kidney damage by activating the NLRP3 inflammasome, where supplementation with Parabacteroides distasonis significantly reduced SUA levels." (PMID 40950584, 2025).